MIR643 (microRNA 643)
Synonyms: hsa-mir-643; MIRN643; mir-643
Gene: MicroRNA gene on chromosome 19 (52,281,797 to 52,281,893, forward strand). Ensembl gene ENSG00000208002.
Gene Ontology:
Biological process: miRNA-mediated post-transcriptional gene silencing
Cellular component: RISC complex
Homologues: Orthologues: chimpanzee ptr-mir-643 (98% identical), macaque mml-mir-643 (92% identical).